SOCS1 (suppressor of cytokine signaling 1)
Diseases named in the same sentence as SOCS1 in open-access papers (continued):
Sharing a sentence is not in itself a finding about the gene and the disease.
tumor (continued). "SOCS1, a key inhibitory molecule of MAPK/ ERK signaling, can inhibit cell proliferation by suppressing cell cycle progression, promoting cell apoptosis, or promoting tumor cell metastasis and invasion when it is expressed aberrantly in cells." (PMID 29506516, 2018). "Considering that SOCS family proteins function as a terminator of LR, the suppression of SOCS1, SOCS3, and SOCS7 expression in remnant livers may be involved in the accelerated tumor development in HBx transgenic mice after PH." (PMID 29729074, 2018). "However, considering the difference in the expression patterns of SOCS1 and SOCS3 in tumor cells and immunocytes, different therapeutic approaches should be implemented according to the types of target cells." (PMID 28228755, 2017). "The relative contribution of the different downstream targets of SOCS1 in mediating tumor suppression in diverse cancers has not been studied yet." (PMID 28235401, 2017). "Therefore, the present study focused on the similarity and disparity of the expression, distribution, function, and regulation of SOCS1 and SOCS3 between tumor cells and immune cells in the tumor microenvironment." (PMID 28228755, 2017). "To compare the CIMP classifications derived from our clustering analysis to those derived from the Weisenberger panel of genes, we analysed the methylation status of our tumour samples using MethyLight at each gene from this panel (CACNA1G, NEUROG1, SOCS1, IGF2, RUNX3)." (PMID 28351398, 2017). "Given that SOCS1, SOCS6, and PTEN are known to be critical tumor suppressors, we reasoned that restoring their expression by downregulating miRNA expression could be a good cancer treatment strategy." (PMID 27811366, 2016). "By regulating this negative feedback mechanism, SOCS1 can influence the transduction of proliferative signals and affect the survival, differentiation and transformation of T cells or tumor cells." (PMID 25893382, 2015). "SOCS1 methylation was correlated with progression of HCC, age and tumor size." (PMID 24635883, 2014). "More data was particularly evident in SOCS1 and SOCS3 roles as tumor suppressors." (PMID 20433750, 2010). "Mechanistically, it induces suppressor of cytokine signaling 1 (SOCS1) expression in tumor cells and MDSCs, reducing immunosuppressive cytokine production and promoting chemokine secretion that facilitates monocyte, macrophage, and T cell recruitment to the tumor site." (PMID 41204180, 2025). "Additionally, tumor-derived exosomal-miR-6794-5p translocates to macrophages in the surrounding tumor microenvironment and activates the JAK1/STAT3 pathway by inhibiting SOCS1 expression, resulting in M2 polarization of macrophages." (PMID 38521953, 2024). "Targets of miR-155, such as histone deacetylase 4 (HDAC4), suppressor of cytokine signaling-1 (SOCS1) and immune cells, play a crucial role in DLBCL pathogenesis, since miR-155 regulates key pathways, transcription factors and cytokine expression and shapes the tumor microenvironment in DLBCL." (PMID 39767565, 2024). "Our FACS analysis of tumor-infiltrating OT1s found that inactivation of SOCS1 in transferred CD8+ T cells did not affect Slamf6+CD39–PD-1med Texprog cell frequency while enhancing the accumulation of Slamf6–CD39+PD-1hi cells containing Texint, Texeff, and CD8+ T cells." (PMID 38099496, 2023). "Collectively, these data identify SOCS1 as a target that, upon CRISPR/Cas9-mediated inactivation, enhances the ability of TILs to expand under manufacturing conditions and to drive the infiltration and accumulation of tumor-specific CD8+ T cells within solid tumors in an in vivo setting." (PMID 38099496, 2023). "However, SOCS1 mediated negative signaling feedback has been shown to be important for inflammation reduction and also to limit nascent tumor growth." (PMID 35844493, 2022).
tumor (continued). "In addition, SOCS1 inhibition and STAT6 activation can promote the polarization of M2-subtype macrophages, enhance the invasion and migration ability of OSCC cells, and accelerate tumor growth." (PMID 36359867, 2022). "Moreover, alterations correlated with distant metastasis emereged with significantly increased expression in SAMRCD1 in low-ITK group, but CD244 and SOCS1 in high-ITK group (p < 0.001), which indicated as oncogene or tumor suppressors in numerous cancers and potential therapeutic targets." (PMID 34702300, 2021). "Nonetheless, compelling evidence for the non-overlapping tumor suppressor functions of SOCS1 and SOCS3 from genetic models prompted us to investigate the relationship between the expression levels of SOCS1 and SOCS3 and the key signaling pathway genes implicated in carcinogenesis." (PMID 32807134, 2020). "Next, we explored whether SOCS1 could be an important molecular marker in predicting the clinical outcome of HCC patients and found that the tumour-free survival in HCC patients with high SOCS1 expression was significantly higher than that in patients with low SOCS1 expression (P = .0042)." (PMID 32096766, 2020). "Treg-selective deletion of essential Treg factors such as Neuropilin-1 (Nrp-1), suppressor of cytokine signaling 1 (SOCS1), enhancer of zeste homolog 2 (EZH2), Eos (IKzf4), or CARMA1 leads to Foxp3 downregulation and inflammatory cytokine secretion, conferring resistance to tumor growth in the host." (PMID 33024109, 2020). "In addition, the DCs in which SOCS1 had been silenced by the YSK12-MEND showed drastically enhanced immuno-stimulative activities and the efficacy of cell therapy using the SOCS1-silenced DC in tumor bearing mice was increased substantially." (PMID 31383907, 2019). "Knockdown of NR1H4 can also attenuate the expression level of SOCS1 and SOCS2 after ZINC24469384 treatment, and the decrease of SOCS2 is sharper than SOCS1, These data indicated that SOCS2 may play more important role in NR1H4 induced anti-tumor effects." (PMID 30787420, 2019). "However, whether SOCS1 and JAK2/STAT3 pathway participate in the proangiogenic switch of CAFs and whether tumor-secreted exosomal miRNAs regulate both regulators are unclear." (PMID 30285793, 2018). "SOCS-1, SOCS-3 may have protective functions in tumor development." (PMID 30788302, 2018). "Thus, specific treatment targeting SOCS1 and SOCS3 might be considerably important in inhibiting tumor development and progression." (PMID 28228755, 2017). "In HCC, elevated miR-155 has been shown to target suppressor of cytokine signaling 1 (SOCS1), thereby activating signal transducer and activator of transcription 3 (STAT3) signaling and enhancing the expression of MMP9, which results in increased tumor invasiveness." (PMID 26950158, 2016). "The tumor suppressor property of miR-29b may be partially explained by its inhibition on IL6-JAK-STAT3 signaling via targeting DNMTs and subsequent demethylation and activation of SOCS1." (PMID 24991558, 2014). "The relevance of C/EBP-β and SOCS1 could be translated to ALD due to the fact that SOCS1 not only acts as a tumor suppressor, but also is a negative regulator of LPS signaling, while chronic alcohol use results in increased inflammatory cytokine production." (PMID 22518321, 2012).
tumor (continued). "Not only have known tumor suppressor genes like Cdkn2a (p16), Itga4 (α 4-integrin), and Igfbp7 been identified as targets of aberrant methylation in cancer by RLGS, but also novel tumor suppressor genes such as TCF21, SLC5A8, ID4, BMP3B, and SOCS1 have been identified by RLGS." (PMID 18053125, 2007). "However, MSCs with SOCS1 knockdown exhibited enhanced immunosuppressive capacity, showing as inhibiting T cell proliferation at extremely low ratio (MSC to T) in vitro, significantly promoting tumor growth and inhibiting delayed-type hypersensitivity response in vivo." (PMID 24826993, 2014). "Thus, it is intriguing to speculate that restoring IGFBP3 expression and/or use of demethylating drugs could contribute to new therapeutic strategies for HB, especially with the existence of additional epigenetically silenced genes in this tumor type, such as HHIP, RASSF1, SOCS1, APC and CASP8." (PMID 22401581, 2012). "KSQ-001 consisted of CD3+ cells with no detectable residual tumor cells, with patient-unique frequency of CD4+ and CD8+ T cells not affected by inactivation of SOCS1." (PMID 38099496, 2023). "Among the genes that showed a negative correlation with SOCS1 and/or SOCS3, nine genes with high expression in tumor tissues predicted poor prognosis, whereas low expression of PIK3R1 was associated with bad prognosis." (PMID 32807134, 2020). "In some cases, the lack of SOCS1 and SOCS3 contributes to the growth of tumor mass induced by cytokines or growth factors, thus confirming the tumor suppressor function of these two molecules." (PMID 28445952, 2017). "Evidence of a direct role of SOCS3 in tumor progression in terms of disruption of cell cycle does not exist, likely due to the fact that SOCS3, differently from SOCS1, cannot localize in the cell nucleus, since it lacks of a nuclear translocation domain." (PMID 28445952, 2017). "Since SOCS1 is also not adequately expressed in BCC and SCC lesions, it would be interesting to evaluate the potential anti-tumor effects of KIR-SOCS1 mimetic peptides, such as PS5, in BCC and SCC lines." (PMID 28445952, 2017). "The expression of SOCS1 mRNA did not significantly differ with increasing Nottingham Prognostic Index (NPI) or between normal background breast tissue and tumour tissues of patients with different NPI levels." (PMID 20433750, 2010). "Finally, evidence of a direct role of SOCS3 in tumor progression in terms of disruption of cell cycle does not exist, likely due to the fact that SOCS3, differently from SOCS1, cannot localize in the cell nucleus, since it lacks a nuclear translocation domain." (PMID 38975347, 2024). "Unlike SOCS1, other SOCS proteins display unambiguous tumour-suppressor function in CRC." (PMID 31091767, 2019). "However, due to the complex role of SOCS1 in CRC progression, this protein may not be a good predictor of tumour response to JAK inhibitors in this cancer." (PMID 31091767, 2019). "The frequency of the methylation in tumour tissue was 57.1% in p16, 2.4% in DAP-kinase, 23.8% in GSTP1, 90.5% in APC, 45.2% in RIZ1, 64.3% in SFRP1, 59.5% in SFRP2, 28.6% in SFRP5, 47.6% in RUNX3, and 54.8% in SOCS1, while in MGMT, no aberrant methylation was detected." (PMID 17968429, 2007). "These postulated alterations in RNA processing, their translation to polypeptides and proteasomal degradation promoted by SOCS1 could promote the generation of non-canonical antigenic peptides, which in turn would impact the MHC-I peptidome, potentially contributing to tumor immune surveillance." (PMID 38415248, 2024).
cancer (191 papers, 2003 to 2026). A tumor composed of atypical neoplastic, often pleomorphic cells that invade other tissues. "In HBC, it is associated with cancer cell proliferation, invasion and angiogenesis by targeting the suppressor of cytokine signaling 1(SOCS1)." (PMID 40115961, 2025). "In the context of cancer, Let-7b-5p was also shown to target SOCS1, the inhibition of which is associated with a pro-angiogenic switch." (PMID 39120274, 2024). "Our findings add CDKN1A induced by SOCS1 deficiency to this list of NRF2 activators in cancer cells." (PMID 36765862, 2023). "Promoter methylation of the suppressor of cytokine signaling-1 (SOCS1) gene contributed to gene silencing, which was associated with the occurrence of malignant tumors." (PMID 36715873, 2023). "Other studies have demonstrated that elimination of SOCS1 leads to perinatal death and increases susceptibility to cancer in mice." (PMID 37504269, 2023). "Epigenetic inactivation of SOCS1 is known to be caused by Cp-G island hypermethylation in many types of cancers." (PMID 35626153, 2022). "As consistently shown by qRT-PCR and Western blot, SOCS1 was minimally expressed in most HCC cells, indicating that the SOCS1 level is associated with the cancer suppressor phenotype in HCC cell lines." (PMID 32096766, 2020). "SOCS1 induces apoptosis and inhibits the growth of cancer cells, whereas SOCS6 is associated with disease recurrence." (PMID 33294082, 2020). "Knockout of SOCS1 leads to perinatal lethality in mice and increased vulnerability to cancer, while several SNPs associated with the SOCS1 gene have been implicated in human inflammation-mediated diseases." (PMID 31105556, 2019). "Given that SOCS1 gene repression occurs in many cancers by diverse mechanisms, clearly there is a need for developing and testing more sensitive and specific SOCS1 antibodies for diagnostic purpose in surgical pathology." (PMID 28235401, 2017). "Predicted mRNA targets of the miRNAs significantly regulated after ATM depletion included many genes associated with cancer formation and progression, such as SOCS1 and the proto-oncogene MAF." (PMID 23741392, 2013). "According to the national cancer institute, somatic SOCS1 mutations could be identified in several B cell malignancies." (PMID 34421895, 2021). "This partially explains why SOCS1-/- mice are relatively more susceptible to cancer." (PMID 31105556, 2019). "Pin1 is frequently up-regulated in various cancer cell types whereas the E3-ubiquitin-ligase of RelA/p65 known as suppressor of cytokine signalling-1 (SOCS-1) is down-regulated or mutated, all of which favours the constitutive activation of NF-κB in those cancers." (PMID 30717249, 2019). "Altered SOCS1 expression has been reported in a wide range of human cancers and it may represent a diagnostic or prognostic biomarker." (PMID 25893382, 2015). "Comprehensive understanding of the mechanisms underlying SOCS1 tumour-promoting vs. tumour suppressor activity in cancer cells may unravel the molecular “switch” dictating whether SOCS1 promotes pro-oncogenic or tumour suppressor functions." (PMID 26391193, 2015). "These contradictory findings in different cancer cell types may be due to the onset of different tumors at different origins, and these studies clearly indicate that SOCS1 warrants its role in cancer onset and it might be a novel diagnostic or prognostic biomarker for cancer therapies." (PMID 37720228, 2023).
cancer (continued). "have demonstrated that the Suppressor of Cytokine Signaling 1 (SOCS1), Suppressor of Cytokine Signaling 6 (SOCS6), and Phosphatase and Tensin Homolog (PTEN) are implicated in various human malignant tumors, including NSCLC." (PMID 39963112, 2025). "NOX4 showed the highest frequency of methylation, while the expression of SOCS1 positively correlated with the promoter methylation across 20 types of cancer in TCGA." (PMID 40463869, 2025). "This process is complicated: when miR-146 is upregulated in cancer cells, SOCS1 (Down)/Jak-Stat (Up)/cancer cell proliferation (Up) is observed, which is counterproductive for metastasis suppression." (PMID 40940831, 2025). "In contrast, suppressor of cytokine signaling 1 (SOCS1) suppresses the Jak-Stat signaling pathway, so the activation of SOCS1 in cancer cells suppresses cancer cell growth." (PMID 40940831, 2025). "Herein, we discuss the importance of the findings collected in the past on SOCS1 and SOCS3 function in the inflammatory responses associated to skin immune-mediated diseases and malignancies, for the development of the JAK inhibitor drugs." (PMID 38975347, 2024). "In this review, we will retrace the numerous studies obtained during the last two decades and aimed at deciphering the structure and function of SOCS1 and SOCS3 in the inflammatory contexts associated to skin immune-mediated diseases and malignancies." (PMID 38975347, 2024). "The correlation between SOCS1 expression with pan-cancer TMB and MSI was assessed using data from the TCGA database." (PMID 39654174, 2024). "The combined effects of SOCS1-mediated redox regulation likely lower the threshold level of ROS tolerance in cancer cells with intact SOCS1." (PMID 38254783, 2024). "SOCS1 has also implications in cancer, where its dysregulation can contribute to abnormal immune responses." (PMID 38975347, 2024). "By analyzing cancer genome atlas datasets, a study revealed a correlation between the expression of SOCS1 and SOCS3 and the prognosis of HCC patients, where high expression of SOCS1 was associated with a favorable prognosis." (PMID 39307915, 2024). "An initial exploration into the relationship between SOCS1 expression and pan-cancer immune scores revealed a positive correlation with the immune scores of a majority of cancers, including CHOL, LGG, and GBM." (PMID 39654174, 2024). "Notably, proteins modulated by SOCS1, uniquely in cisplatin-treated cells, showed a significant enrichment of ‘peroxiredoxin activity’, which is recognized as an important pathway in cellular redox homeostasis and is implicated in cancer development and progression." (PMID 38254783, 2024). "The expression and biological functions of SOCS1 were examined through an array of techniques including pan-cancer analysis, functional enrichment, gene set variation analysis, and immune microenvironment examination." (PMID 39654174, 2024). "Conversely mimetics of negative regulators as SOCS1 and 3 are currently demonstrating growing therapeutic interest in inflammatory-related disorders and cancer, respectively." (PMID 38983855, 2024). "As a negative regulator of type 1 interferon signalling and inflammation, SOCS1 has been shown to modulate cell death in cancer and in acute stress." (PMID 39284830, 2024). "On the other hand, many lines of evidence suggest that SOCS1 expression in cancer cells can positively impact the development of antitumor immune responses, for which we present evidence in the following sections." (PMID 38415248, 2024). "SOCS1 expression is predominantly regulated in cancer cells, indicating its potential role in cancer progression." (PMID 39414916, 2024).